MOB2 (MOB kinase activator 2)
Description:
Stimulates the autophosphorylation and kinase activity of STK38 and STK38L.
Synonyms: HCCA2
Tractability: PROTAC: ubiquitination databases record sites on it; its protein half-life has been measured.
Gene: Protein-coding gene on chromosome 11 (1,469,457 to 1,501,247, reverse strand). Ensembl gene ENSG00000182208.
Subcellular location: Nucleus; Cytoplasm, perinuclear region
Subcellular location (Human Protein Atlas): Nucleoli; Cytosol; Nucleoplasm
Gene Ontology:
Molecular function: protein binding; protein kinase activator activity
Cellular component: cytosol; nucleolus; nucleoplasm; cytoplasm; neuron projection terminus; nucleus; perinuclear region of cytoplasm
Genetic constraint (gnomAD): Loss-of-function variants: 11 observed, 19.35 expected, observed/expected ratio (o/e) 0.57, 90% interval 0.36 to 0.94. The upper end of that interval is the gene's LOEUF score, 0.94, which puts it in group 3 of 6, group 1 being the genes least tolerant of losing a copy. Missense variants: 269 observed, 308.35 expected, observed/expected ratio (o/e) 0.87, 90% interval 0.79 to 0.96. Synonymous variants: 149 observed, 139.09 expected, observed/expected ratio (o/e) 1.07, 90% interval 0.94 to 1.23.
Homologues: Orthologues: chimpanzee MOB2 (99% identical), macaque MOB2 (88% identical), mouse Mob2 (87% identical), rat Mob2 (87% identical), guinea pig MOB2 (86% identical), pig MOB2 (85% identical), rabbit MOB2 (85% identical), tropical clawed frog mob2 (68% identical), zebrafish mob2a (68% identical), dog MOB2 (62% identical), zebrafish mob2b (61% identical), Caenorhabditis elegans mob-2 (30% identical). Paralogues in human: MOB1A (34% identical), MOB1B (34% identical), MOB3A (27% identical), MOB3B (27% identical), MOB3C (26% identical), MOB4 (18% identical).
Diseases named in the same sentence as MOB2 in open-access papers:
MOB2 is named in the same sentence as 17 diseases in open-access papers, as found by Europe PMC text mining. Sharing a sentence is not in itself a finding about the gene and the disease. The quoted sentences say what the papers report.
glioma (2 papers, 2020 to 2022). A benign or malignant brain and spinal cord tumor that arises from glial cells (astrocytes, oligodendrocytes, ependymal cells). "Several factors, such as integrin, E-cadherin, EGFR, IGFR, Trk, TGF-β, the Hippo pathway, NF-κB, eEF-2 kinase, MOB2, hypoxia, acidosis, ROS, Hsp and protective autophagy, have been shown to induce anoikis resistance in glioma." (PMID 36046036, 2022). "Nuclear factor-κB (NF-κB), elongation factor-2 kinase (eEF-2 kinase) and Mps one binder kinases 2 (MOB2) are known promotors of glioma." (PMID 36046036, 2022). "To further investigate the clinical relevance of MOB2 in glioma, we performed Kaplan-Meier survival analyses of MOB2 mRNA expression data from the TCGA (n = 690, low expression: 173; high expression: 517)." (PMID 32286266, 2020). "Low MOB2 expression significantly correlated with a poor prognosis for glioma patients in the TCGA data set (p = 0.00999)." (PMID 32286266, 2020). "Analysis of MOB2 expression in glioma patient specimens and bioinformatic analyses of public datasets revealed that MOB2 was downregulated at both mRNA and protein levels in GBM." (PMID 32286266, 2020). "Studies have revealed that several regulators take part in anoikis resistance in glioma; these include integrin, E-cadherin, EGFR, IGFR, Trk, TGF-β, the Hippo pathway, NF-κB, eEF-2 kinase, MOB2, hypoxia, acidosis, reactive oxygen species (ROS), heat shock proteins (Hsps) and protective autophagy." (PMID 36046036, 2022). "To assess the expression of MOB2 in glioma clinical samples, we performed an immunohistochemical (IHC) analysis on normal brain tissues, low grade gliomas (LGGs, WHO grade I and II gliomas, n = 16) and glioblastoma (GBMs, WHO grade IV gliomas, n = 19) samples." (PMID 32286266, 2020).
ovarian carcinoma (2 papers, 2020 to 2021). A malignant neoplasm originating from the surface ovarian epithelium. "Furthermore, the human MOB2 gene appears to display loss-of-heterozygosity in more than 50% of bladder, cervical and ovarian carcinomas (TCGA)." (PMID 34363951, 2021). "Our findings together with publicly available cell line profiling data would suggest that ovarian cancer cells display a link between MOB2 mRNA levels and sensitivity to PARP inhibition and a standard genotoxic therapeutic agent, such as cisplatin." (PMID 34363951, 2021). "Reduced MOB2 expression correlates with increased overall survival in patients suffering from ovarian carcinoma." (PMID 34363951, 2021). "In addition, examination of the publicly available CellMiner database found that ovarian cancer lines with lower MOB2 mRNA levels seem to be more sensitive to olaparib or cisplatin treatments when compared to cells expressing higher MOB2 mRNA levels." (PMID 34363951, 2021).
periventricular nodular heterotopia (2 papers, 2018 to 2019). Periventricular nodular heterotopia (PNH) is a brain malformation, due to abnormal neuronal migration, in which a subset of neurons fails to migrate into the developing cerebral cortex and remains as nodules that line the ventricular surface. "MOB2 loss-of-function impairs the correct neuronal positioning within the developing cortex, thereby associating MOB2 inactivation with a disorder such as periventricular nodular heterotopia." (PMID 31185650, 2019). "Here, we report biallelic variants in a Hippo signaling factor—MOB2—in a patient with one such disorder, periventricular nodular heterotopia (PH)." (PMID 29593499, 2018).
brain cancer (1 paper, 2020). A primary or metastatic malignant neoplasm affecting the brain. "In addition, MOB2 regulated the neuritogenesis of a mouse neuroblastoma cell line Neuro2A via interaction with NDR224, suggesting that MOB2 might play a role in brain cancer." (PMID 32286266, 2020).
glioblastoma (1 paper, 2020). The most malignant astrocytic tumor (WHO grade IV). "Here we show that MOB2 functions as a tumor suppressor in glioblastoma (GBM)." (PMID 32286266, 2020).
hepatocellular carcinoma (1 paper, 2020). A malignant tumor that arises from hepatocytes. "In hepatocellular carcinoma, MOB2 negatively regulates phosphorylation of MOB1 and LATS which could lead to YAP activation and increased motility of cancer cells." (PMID 32841529, 2020).
liver cancer (1 paper, 2019). An epithelial or non-epithelial malignant neoplasm that arises from the liver. "However, due to the lack of MOB2 loss-of-function animal models it is currently unclear whether deregulated MOB2 expression can drive liver cancer development." (PMID 31185650, 2019).
lung carcinoma (1 paper, 2026). "In this study, we examined the role of the NDR/Hippo-associated cofactor human MOB2 (hMOB2) in shaping PARP inhibitor responses in lung cancer cells." (PMID 41899447, 2026).
type 2 diabetes (1 paper, 2025). "Variants in KLF14 and MOB2, which previously were shown to have parent-of-origin effects on type 2 diabetes, here showed parent-specific effects on lipid levels, with the risk-increasing allele being associated with lipid levels." (PMID 40175764, 2025). "Previous studies showed that the T allele of the MOB2 variant increased type 2 diabetes risk when inherited from the father but decreased type 2 diabetes risk when inherited from the mother." (PMID 40175764, 2025).
van Maldergem syndrome (1 paper, 2018). "FAT4 and DCHS1 are directly implicated in the cause of Van Maldergem syndrome, a developmental disorder characterized by PH and function upstream of MOB2 in the Hippo signaling pathway." (PMID 29593499, 2018).
cancer (2 papers, 2020). A tumor composed of atypical neoplastic, often pleomorphic cells that invade other tissues. "So far, although other members of MOB family including MOB1 and MOB3 have been implicated in cancer, the roles of MOB2 in cancer have not been thoroughly described." (PMID 32286266, 2020). "Mps one binder 2 (MOB2) regulates the NDR kinase family, however, whether and how it is implicated in cancer remain unknown." (PMID 32286266, 2020).
tumor (2 papers, 2020 to 2025). "As a result of dampening the anti‐tumor immune response, the MoB2‐induced reductive environment actually facilitated cancer metastasis in a breast cancer model‐mice treated with the nanozyme showing increased tumor cell spread to the lungs." (PMID 40569215, 2025). "In this study, combining in vitro and in vivo analyses, we uncover MOB2 as a tumor suppressor in GBM." (PMID 32286266, 2020). "Collectively, these findings suggest a role of MOB2 as a tumor suppressor in GBM via regulation of FAK/Akt signaling." (PMID 32286266, 2020). "MOB2-overexpressing SF-767 cells inoculated in nude mice showed a significant decrease in tumor growth compared to control cells." (PMID 32286266, 2020). "Taken together, these data suggest that MOB2 functions as a tumor suppressor in GBM." (PMID 32286266, 2020). "Here, we report that MOB2 acts as a novel tumor suppressor in GBM." (PMID 32286266, 2020).
infection (1 paper, 2012). The state of being infected such as from the introduction of a foreign agent such as serum, vaccine, antigenic substance or organism. "The interpretation of these data is that the mob2 mutation had reverted to wild type in the four animals during the course of infection." (PMID 23055925, 2012). "A strain derived from amoeba with a point mutation in the MOB2 gene was unable to cause disease in a murine model, unless during the course of infection the mutation reverted to wild type." (PMID 23055925, 2012). "Sacrifice of the remaining and asymptomatic animals at day 70 and characterization of fungal material in lung and brain tissue shows that three mice had cleared the infection, one carried wild type cells, and the other two still maintained the original mob2 mutant phenotype and genotype." (PMID 23055925, 2012).
MOB2 also shares sentences with these, for which no sentence is quoted: craniofacial microsomia (1 paper); hearing loss (1); neuroblastoma (1); retinitis pigmentosa (1).